IL17A (interleukin 17A)
Diseases named in the same sentence as IL17A in open-access papers (continued):
Sharing a sentence is not in itself a finding about the gene and the disease.
infection (continued). "The higher IL-17A levels in Bangladeshi children is possibly explained by a higher proportion of CD4+ memory T cells in this high risk population due to frequent infections during early life." (PMID 26069966, 2015). "Vaccinated mice transiently exhibited IL-17A-mediated pathology that presented as increased weight loss and morbidity during early stages of infection." (PMID 24465206, 2014). "In recent years, it has been reported that responses involving IL-17a/TH17 appear to complement the response of IFN-γ/TH1 axis that is characteristic of the combat against infection caused by Salmonella." (PMID 25162711, 2014). "Despite both types of mice show a higher fungal burden early in infection, as compared to wild-type mice, IL-17F-deficient, more than IL-17A-deficient, mice showed signs of inflammation and PMN recruitment associated with high levels of IL-17A." (PMID 23853597, 2013). "Several studies implicated IL-17A in IL-8 driven neutrophil infiltration to the lungs in other infections." (PMID 24194936, 2013). "RSV pathology is enhanced in mice deficient in CCR7 and STAT1 through elevated IL-17A production at 8 days post infection, as well as by Th17 cells that originate from prior sepsis." (PMID 24194936, 2013). "The more severe infection in IL-17A−/− mice was associated with a significant reduction in CXCL1 (KC) production and impaired neutrophil recruitment to the lungs post challenge." (PMID 23592988, 2013). "Our results using mice deficient in IL-17RA signaling show that the percentage of IL-17A+ neutrophils were decreased by approximately 47% compared to wild-type mice during infection with C. neoformans strain H99γ, which supports this conclusion." (PMID 23216912, 2012). "Finally, loss of IL-17A signaling specifically in T cells during MHV68 infection resulted in a similar attenuation of viral latency and reactivation as well as the germinal center response in the spleen." (PMID 41335125, 2025). "However, ETBF infection-induced IL-17A inflammation was comparable between B-cell-deficient mice and WT mice." (PMID 38203534, 2023). "Notably, IL-17A recruit neutrophils to the site of pathogenic infection, where it forms neutrophil extracellular traps (NETs)." (PMID 38029108, 2023). "Furthermore, the level of IL-17A in the lungs of WT mice was significantly reduced following infection with a P. aeruginosa strain harboring mutations in the QS genes lasR and rhlR compared with the level of IL-17A following infection with P. aeruginosa PAO1." (PMID 36033859, 2022). "We previously reported that IFN-γ deficient mice produce large amounts of IL-17A upon LgyLRV1+ infection and that this cytokine governs the formation of the metastatic nodules as evidenced by its genetical deletion or chemical inhibition that dramatically reduced the number of metastatic nodules." (PMID 36034693, 2022). "Moreover, neutrophilic lung inflammation was reduced in IL-17A-deficient mice as well as in anti-IL-17A antibody-treated mice exposed to CS for 4 days followed by infection with NTHi." (PMID 35883573, 2022). "Besides the massive influx of neutrophils, additional reasons for the enhanced susceptibility of IL-17A−/− mice to high-dose infection with Mtb H37rv are conceivable." (PMID 36139450, 2022). "Whereas the outcome of a low-dose infection with the lab-adapted strain Mtb H37Rv is unaffected in mice deficient for IL-17A, the cytokine is required for control of a high dose infection with 1 × 103 colony-forming units (CFU) H37Rv and of infection with the hypervirulent W/Beijing strain HN878." (PMID 34351501, 2021). "Furthermore, Siglec-F+ neutrophils were significantly reduced in the nasal tissue of Il17A−/− during infection with B. pertussis and this is associated with significantly higher bacterial burden in the nose." (PMID 33976385, 2021).
infection (continued). "The association of IL-17 with infection is further confirmed when increased survival rates and decreased bacterial burdens in ducks infected with R. anatipestifer occur after expression levels of IL-17A and IL-17F cytokines are downregulated using berberine treatment." (PMID 34805416, 2021). "We measured the levels of IFN-gamma, IL-4, IL-10, IL-17A, IL-23, and IL-9 in the serum samples and PBMCs from the KO and WT mice at different stages of infection to conduct and extensive analysis of how USP21-deficient Tregs affect the resistance of mice to S. japonicum." (PMID 33628844, 2021). "aureus infection were higher for vaccinated IL-17A-deficient mice than for vaccinated WT mice." (PMID 34358191, 2021). "Up to now autoantibodies to four major groups of cytokines—IFN-γ, GM-CSF, to a group of TH-17 cytokines comprising IL-17A, IL-17F, IL-22, IL-23, and to IL-6—have been found to be causative or closely associated with increased susceptibility to selective infection." (PMID 32419033, 2020). "Therefore, high levels of IL‐17A, IL‐10 and sE‐selectin identified both patients at higher risk of persistent bacteraemia and patients with endovascular reservoirs of infection despite surveillance blood cultures rapidly turning negative." (PMID 32082571, 2020). "Upregulation of IL21 and IL17A was strongly associated with infection and female sex, suggesting the involvement of Th17 cells in the antichlamydial immune response and that Th17 cell responses might be heightened in females relative to those in males." (PMID 31964744, 2020). "Thus, IL-17A producing effector/Treg cells can contribute to excessive inflammation causing host tissue damage during infection." (PMID 32542025, 2020). "Thus, further infection experiments should be performed in IL-17A-deficient BALB/c mice to elucidate the role and interaction of IL-5 and IL-17A." (PMID 29931394, 2018). "Indeed, mice deficient in IL-17A and/or IL-17F are highly susceptible to infection with a wide array of fungi and extracellular bacteria, as well as viruses and parasites." (PMID 30364284, 2018). "Additionally, a strong Th17 cell response is induced upon infection and mice that lack the Th17 cytokines IL17A/F showed an enhanced susceptibility towards infection with C. rodentium." (PMID 28520792, 2017). "IL-17A has also been implicated in the antibody response to S. pneumoniae capsular polysaccharide and can effectively enhance bacterial phagocytosis and killing functions to resist lethal infection." (PMID 28659923, 2017). "To assess whether blocking the IL-17 cytokine family axis may affect host susceptibility to M. tuberculosis H37Rv strain infection, we investigated the effect of neutralizing IL-17A or IL-17F during acute infection, in comparison to TNFα neutralization." (PMID 27853279, 2016). "Interestingly, in the murine models of L. braziliensis and L. amazonensis, the infections were linked with IL-17A-producing T-cells." (PMID 27658195, 2016). "The coexistence of a mixed Th2/Th17 in reinfected mice with increased levels of IL-4 and IL-17A after each infection might also be associated to tissue injury and remodeling." (PMID 26814713, 2016). "In this regard, iBALT induced by infection with modified vaccinia virus Ankara or influenza virus is not affected by deficiency of IL-17A, while Pseudomonas aeruginosa-induced iBALT is dependent on IL-17 signaling." (PMID 27579026, 2016). "These cells that produce both IL-17A and IFN-γ are suspected to be more pathogenic than IL-17A single producers because they induced stronger inflammatory reactions but may also be more efficient at combating infections." (PMID 26375594, 2015). "Similarly, lethal infection of IL-10-deficient mice with the intestinal whipworm parasite Trichuris muris led to increased parasite-antigen-induced IFNγ and IL-17A." (PMID 23345540, 2013).
infection (continued). "Chickens vaccinated with profilin plus ISA 71 and infected with all 3 Eimeria parasites had greater levels of intestinal IEL gene transcripts encoding IFN-γ, IL-2, IL-10, and/or IL-17A at 3 days post-infection compared with infected birds vaccinated with profilin alone." (PMID 23593150, 2013). "Where a reduced functioning of the IL-12/IFN-gamma axis has been a preferred mechanistic explanation why newborns are particularly susceptible to pathogen infections, diminished functioning of this pathway function results in the increased deployment of the IL-23/IL-17A immune axis." (PMID 24194936, 2013). "The levels of IL-17A were also reduced in mice deficient for both IL-1α and/or IL-1β or IL-1R1 at 5 weeks post-infection and in IL-1α or IL-1β single deficient mice at 8 weeks post-infection." (PMID 25400917, 2013). "Whether the observation that IL17A rs1974226 genotype altered susceptibility to infection, is specific to Gram-positive bacteria is unknown." (PMID 22026963, 2011). "Of the four SNPs, the major G allele of IL17A rs1974226 G/A was significantly associated with increased susceptibility to infection by Gram-positive bacteria (percentages of positive culture: AA 38.5%, AG 46.4%, GG 64.2%, uncorrected P = 0.0037, Bonferroni corrected P = 0.014)." (PMID 22026963, 2011). "Card9-deficient mice also had reduced expression of Il17a and the associated transcription factor RORγτ in lung homogenates at day 7 post-infection compared to wild-type mice; however, Il—17a-deficient mice actually had a significantly lower lung fungal burden at day 14 post-infection." (PMID 38921420, 2024). "We find that both resident and recruited γδ T cells are part of this induced wound healing response via production of IL-17A and IL-22, as well as the induction of IL-10 in other cells, and that a deficit in γδ T cells causes a profound increase in tissue pathology following infection." (PMID 38543790, 2024). "The detection of IL-17A in milk produced by CM cases along with a predominant type 2 immune response, suggests that the inflammation detected in CM cases may be associated with a well-established acute extracellular infection." (PMID 39896819, 2024). "Thus, excessive infection of C. albicans may cause more IL-17A production and release, which further activates the IL-17A/IL-17RA signaling pathway in OC cells to induce macrophage infiltration." (PMID 37067414, 2023). "It is, therefore, tempting to speculate that IL-17A could also play a role in mediating the weight loss experienced by patients infected with T. brucei, although this remains to be studied in more detail in the context of natural infections in humans." (PMID 37923768, 2023). "Activation of γδ T cells for IL-17A production is severely impaired in Itk-deficient mice and very likely responsible for the resultant neutrophil recruitment early after infection(s), as well as the increased neutrophil resident Mtb population later in infection." (PMID 32038633, 2019). "The present investigation compares the effect of anti-IL-17A or TNFα neutralizing antibodies side-by-side, including TNFα-deficient mice as susceptible controls, and in addition the role of IL-17F, in a commonly used M. tuberculosis H37Rv strain infection model." (PMID 27853279, 2016). "Consistently, Trmt61aΔRorc mice displayed markedly reduced percentages and numbers of total ILC3s and IL-22-producing ILC3s in the colon five days post-infection, compared to controls, along with a decreasing trend in the numbers of IL-17A-producing ILC3s." (PMID 41484094, 2026). "Post-infection depletion of neutrophils rescued mice from lethal infection by significantly reducing the bacterial burden and levels of IL-17A, IL-6, and TNF-α in peripheral blood." (PMID 42308351, 2026). "Disruption of the gut microbiota impaired hepatic γδ T cell IL-17A production, reduced neutrophil mobilization, and compromised host resistance to infection." (PMID 41657029, 2026).
infection (continued). "The lung tissues exhibited significantly higher levels of pro-inflammatory cytokines compared to liver and spleen tissues, with elevated IL-17A levels observed exclusively in the lung tissues of moribund mice at infection stage 1." (PMID 42308351, 2026). "Together, these data highlight a proviral role for global and more specifically T cell-intrinsic IL-17A signaling during MHV68 infection." (PMID 41335125, 2025). "Further, Ptpn2∆IEC mice displayed lower IL-22, IL-6, IL-17A cytokine expression post mAIEC infection compared to Ptpn2fl/fl controls." (PMID 40955058, 2025). "This concurred with a Th17 skewing, upregulated Il17a, and greater colonic pathology during infection." (PMID 40883285, 2025). "To further demonstrate that the IL-6–Jak2–Stat3 axis is involved in Th17 cell development during PmA infection, we used IL-6-KO mice and recombinant IL-17A." (PMID 41402924, 2025). "In conclusion, our current study revealed that Th17 cell/IL-17A is critical in the fight against PmA and that the IL-6–Jak2–Stat3 axis promoted Th17 cell/IL-17A activation during PmA infection in vivo." (PMID 41402924, 2025). "In fish, several IL-17 family members—such as IL-17A/F2a, IL-17C1, IL-17C2, and IL-17D—have been identified and shown to be responsive during infection." (PMID 40943072, 2025). "The expression of IL-1β, IFN-α2, IFN-γ, TNF-α, MCP-1 (CCL2), IL-6, IL-8 (CXCL8), IL-10, IL-12p70, IL-17A, IL-18, IL-23, and IL-33 was assessed in apical washes at different time points after infection using a 13-plex immunoassay." (PMID 40143308, 2025). "While we did not investigate cell associated IL-17A secretion, our data and others support the possible role for IL-17A/IL-17A-producing cells in protection from infection." (PMID 40196541, 2025). "When we knocked out C3, we found that inflammatory cytokines such as TNF-α, IL-1β, IL-17A, and IL-6 were upregulated on day 1 post-infection." (PMID 40008883, 2025). "The quantity of IL-17A-producing γδ T cells began to increase by day 3 post-infection and peaks by day 5 post-infection." (PMID 40245023, 2025). "We analysed mRNA expression of 9 inflammatory markers (TGF-β1, TNF-α, IL-1β, IFN-γ, IL-6, IL-23, IL-17a, iNOS and ColA1) in kidney of experimental mice at 15 days post infection." (PMID 40445994, 2025). "Mechanistic studies revealed that the IL-6–JAK2–STAT3 axis contributed to Th17 cell/IL-17A activation in PmA infection." (PMID 41402924, 2025). "This increase in IL-17 (a key player in mucosal immunity) levels with every antigen challenge (either from the vaccine or natural infection) suggests a potential role for trained mucosal immunity." (PMID 41012170, 2025). "IL-17A has been shown to contribute to protection of C57BL/6 mice from HN878 infection from 30 days after infection; however, our data suggest that it is unlikely to mediate the very early differences observed in the pulmonary immune response in our study." (PMID 40986319, 2025). "Here, we show that the increased expression of IFNγ and IL-17A coincides with the formation of immature granulomas during the intermediate phase of the infection." (PMID 39807873, 2025). "The qPCR further highlighted that inflammatory cytokines such as IL-1β or IL-17a are expressed at the highest levels during early infection at day 1, as expected." (PMID 40586608, 2025). "Exogenous IL-17A antagonized the increased mortality, suggesting that IL-6 is important for Th17 cell/IL-17A activation during PmA infection." (PMID 41402924, 2025). "For example, IL‐17A is expressed 5 h after inoculation of rhesus macaque ileal loops and 48 h after oral infection of mice with Salmonella." (PMID 39737849, 2025). "Kangfuxin liquid can inhibit microbial growth and development while promoting IL-17A release and neutrophil counts, thereby exerting its anti-infection effects." (PMID 41480530, 2025).
infection (continued). "We found higher IL-1b levels in adult serum and PBMC cultures post-infection, correlating with age and promoting IL-6, IL-9, and IL-17A secretion when combined with IFNa." (PMID 40834853, 2025). "IL-17A and IL-22 are related to Th17 immune response, which is mainly involved in mucosal immunity and plays critical roles in resisting pathogen infection." (PMID 40718811, 2025). "We show here that mice lacking Tbet respond to WT Mtb infection with a Th17 response and provide protection mediated by IL-17A during early infection." (PMID 40463021, 2025). "The Trm-specific subtyping results also showed that BP-L1 infection caused a significant increase in the IFN-γ (P < 0.05 vs. CS) and IL-17a (P < 0.01 vs. CS) subtypes." (PMID 40568708, 2025). "During PmA infection, IL-17A was significantly increased in PmCQ2-infected lungs and blood, as determined via ELISA and western blot analyses." (PMID 41402924, 2025). "WT mice aerosol infected with WT Mtb were intranasally administered with either PBS control or 1 μg recombinant murine IL-17A daily between days 11 to 20 post infection for a total of 10 doses." (PMID 40463021, 2025). "Plasma concentrations of IL-17A (p=0.03) were higher in patients with uncomplicated infection than in healthy controls." (PMID 39935482, 2025). "Th17 cells, activated early in infection, secrete IL-17A to recruit neutrophils and monocytes, promoting granulopoiesis and inflammation." (PMID 41488476, 2025). "Th-17 differentiation is triggered by IL-6 and IL-23 and produces IL-17A, IL-17F, and IL-22 cytokines that further recruit innate immune cells to the site of infection." (PMID 40586608, 2025). "Our findings confirmed that avian CD8αα+hi γδ T cells not only increase in number but also upregulate IL-17A transcription, highlighting an essential regulatory role during infection." (PMID 40438105, 2025). "To further explore the functional importance of IFN-γ and IL-17 in regulating craniotomy infection outcome, we next examined S. aureus abundance in Ifng–/– and Il17a/f–/– mice." (PMID 39989461, 2025). "Injection site reactions and infections remain the most frequently reported AEs, consistent with ixekizumab’s IL-17A inhibition mechanism." (PMID 40408459, 2025). "IL-17A is a characteristic cytokine secreted by Th17 cells and plays an important function in the anti-infection immunity of the host." (PMID 40509258, 2025). "At the later stage of infection, γδ T cells inhibit the IL-12 production by DCs and the Th1 differentiation through the sustained IL-17A secretion, which attenuates the Th1 response and avoids immune pathological damage." (PMID 41017910, 2025). "Upon infection of the gastric mucosa by Helicobacter pylori, the levels of pro-inflammatory cytokines like IL-17A (also known as IL-17) are significantly elevated, forming a chronic inflammatory microenvironment." (PMID 40227215, 2025). "At the molecular level, using a knockout mouse model, we found that the IL-6–JAK2–STAT3 axis played an important role in Th17 cell/IL-17A activation during PmA infection." (PMID 41402924, 2025). "Together, these results indicate that IL-17A production by Th17 cells confers significant protection against Mtb infection in Tbet−/− mice, at least during early stages of infection." (PMID 40463021, 2025). "Correlation analysis highlighted distinct immunological patterns, with IL-10 acting as a negative regulator of inflammation, while TNF-α and IL-17A reflected infection intensity depending on species and timing." (PMID 41156648, 2025). "Administration of either a recombinant chicken IL-17A or IFN-γ prior to infection with MDV and in combination with a vaccine has led to a reduction in Marek’s disease (MD) severity." (PMID 40733625, 2025). "During pregnancy, IL-17A exhibits dual roles: it promotes inflammatory responses to combat infections while potentially disrupting immune tolerance when dysregulated." (PMID 40894398, 2025).